ALK (ALK receptor tyrosine kinase)
Diseases named in the same sentence as ALK in open-access papers (continued):
Sharing a sentence is not in itself a finding about the gene and the disease.
Histiocytosis (continued). "Here, we report four cases of multisystem ALK-positive histiocytosis without hematopoietic involvement." (PMID 36915094, 2023). "ALK-positive histiocytosis, which shows a broad clinicopathologic spectrum unified by the presence of ALK gene translocation (most commonly KIF5B::ALK) and remarkable response to ALK-inhibitor therapy, has been better characterized in recent studies." (PMID 35732831, 2022). "Thus, it is recommended that ALK immunostaining be performed for histiocytic proliferations not conforming to defined entities, to screen for possible ALK-positive histiocytosis." (PMID 35732831, 2022).
chronic myeloid leukemia (46 papers, 2013 to 2025). "As the deregulated activity of ALK is crucial for the survival of cancer cells, ALK selective targeting has been pursued similarly to what happened for BCR/ABL in chronic myeloid leukemia." (PMID 27662658, 2016). "A vast number of compounds identified through these methods have already made significant strides in treating diseases such as viral infections and cancer, including HIV inhibitors, tyrosine kinase inhibitors for chronic myeloid leukemia, and ALK inhibitors for pancreatic cancer, among others." (PMID 38975181, 2024). "Indeed, imatinib and crizotinib have the same effect in BCR-ABL1 chronic myeloid leukemia and ALK-anaplastic cell lymphoma, respectively." (PMID 37423955, 2023). "Remarkably, phosphatases can influence the response to TKI treatment as reported for PTPN1 (PTP1B), PTPN6 (SHP1) and PTPRC (CD45) for BCR-ABL TKIs treatment in chronic myeloid leukemia or for PTPN11 (SHP2) for acquired resistance to ALK-TKIs in ALK-rearranged non-small cell lung cancer (NSCLC)." (PMID 36698412, 2022). "This includes BCR-ABL in chronic myelogenous leukemia (CML), ALK and ROS1 kinase fusions in non-small cell lung cancer, as well as TRK fusions in solid cancers." (PMID 38110872, 2023). "For example, breakpoint cluster region-Abelson (BCR-ABL) tyrosine kinase and EGFR are overexpressed in imatinib-resistant chronic myeloid leukemia (CML) and crizotinib-resistant anaplastic lymphoma kinase (ALK)-positive NSCLC, respectively." (PMID 36140200, 2022). "The attention on chronic myeloid leukemia and pharmacokinetics was gradually decreasing, but the focus on HER2 and ALK was rapidly increasing." (PMID 35072634, 2022). "By network calculation, the TKIs co-word network was divided into 6 communities: C1 (non-small–cell lung cancer), C2 (targeted therapy), C3 (chronic myeloid leukemia), C4 (HER2), C5 (pharmacokinetics), and C6 (ALK)." (PMID 35072634, 2022). "Although ALK expression has also been reported in chronic lymphoblastic leukemia and anaplastic large cell T lymphoma, it is not common in acute myeloid leukemia and chronic myeloid leukemia or multiple myeloma." (PMID 34832908, 2021). "Fusion genes are often oncogenes, such as BCR:ABL in chronic myeloid leukaemia (CML), TMPRSS2:ERG in prostate cancer, EML4:ALK in non-small-cell lung cancer (NSCLC) and so on." (PMID 24564548, 2013).
lung squamous cell carcinoma (46 papers, 2010 to 2026). "Although the mutation rate of EGFR, ALK, and ROS genes in lung squamous cell carcinoma is low, less than 10%, there are still a few patients with mutant targets who can benefit from targeted drugs." (PMID 36411824, 2022). "Herein, we present the case of a 70-year-old female patient with squamous cell lung cancer harboring the echinoderm microtubule-associated protein-like 4 (EML4)-ALK fusion gene." (PMID 34324792, 2021). "ALK-positive of anaplastic lymphoma kinase (ALK) is rare in lung squamous cell carcinoma (LSCC), with an incidence of less than 1%." (PMID 42266662, 2026). "Tumor heterogeneity, especially in the metastatic phase, is influenced by various factors including histological subtypes (such as adenocarcinoma and squamous cell lung cancer) and genetic mutations (such as those in EGFR, BRAF, KRAS, and ALK translocations)." (PMID 39518079, 2024). "Such promising prognostic and predictive markers are missing in squamous cell carcinoma of the lung (LSCC), with the exception of PD-L1 and rare mutations in Epidermal Growth Factor Receptor (EGFR) and rearrangements in Anaplastic Lymphoma Kinase (ALK)." (PMID 37445817, 2023). "This is a report of lung squamous cell carcinoma patients with CLIP1-ALK fusion gene treated with ALK inhibitors." (PMID 36172736, 2022). "Here, we report a case in which brigatinib had a therapeutic effect on ALK-positive lung squamous cell carcinoma." (PMID 34647426, 2021). "The patient in this report was diagnosed with ALK-positive lung squamous cell carcinoma with brain metastases, and received brigatinib after failure of first-line chemotherapy." (PMID 34647426, 2021). "In conclusion, a good clinical effect was achieved in a patient with ALK positive lung squamous cell carcinoma who received treatment with an ALK inhibitor." (PMID 34647426, 2021). "The estimated prevalence of ALK rearrangement in squamous cell lung carcinoma (Sq-LC) is thought to be as low as ∼0.2%–2.5%." (PMID 29844868, 2018). "The relationship between molecular targeted therapy and status of EGFR or ALK genes in patients with lung squamous cell carcinoma needs further investigation." (PMID 27760592, 2016). "Herein, we report the successful case of a patient with squamous cell lung cancer and ALK gene translocation that experienced a remarkable response to crizotinib treatment after two courses of failed chemotherapy." (PMID 24885608, 2014). "Despite the low reconstruction rate of ALK gene, if applicable, patients with squamous cell lung cancer should have the option of undergoing ALK testing and receiving crizotinib treatment." (PMID 24885608, 2014). "Herein, we report the case of a woman with ALK gene translocation-squamous cell lung cancer who experienced a remarkable tumor response to crizotinib after two courses of failed chemotherapy." (PMID 24885608, 2014). "The definitive efficacy of anaplastic lymphoma kinase (ALK) inhibitors in ALK positive lung squamous cell carcinoma (sqCC) patients remain unclear." (PMID 34647426, 2021). "A few cases of squamous cell lung carcinoma (Sq-LC) with ALK rearrangement have been reported; however, the clinicopathological features and clinical outcomes following treatment with ALK inhibitors are unknown." (PMID 29844868, 2018). "Therefore, similarly to what demonstrated by our group in the study of the 3q chromosomal amplification in squamous cell lung carcinoma, ALK-CNG seems mostly related to polyploidy (whole DNA reduplication) rather than locus specific gene amplification." (PMID 27561692, 2016). "Considering this remarkable response to crizotinib, we can safely conclude that patients with squamous cell lung cancer should have the option of undergoing ALK testing to determine if there is indication for crizotinib treatment even after they have failed chemotherapy." (PMID 24885608, 2014).
lung squamous cell carcinoma (continued). "However, the incidence of driver mutations in squamous cell lung cancers is extremely low, therefore EGFR/ALK/ROS1 mutations should have no impact on the findings reported for the stratified analysis on squamous cell lung cancer." (PMID 35045806, 2022). "In the present study, the tumors in cases NCCLu-237 and NCCLu-253 consisted of an ALK-positive large-cell neuroendocrine carcinoma and an EGFR-mutant squamous cell lung carcinoma, respectively." (PMID 38398169, 2024). "Herein, we report the case of a non-smoking woman with squamous cell lung cancer and ALK gene rearrangement who experienced remarkable response to crizotinib treatment after failed chemotherapy." (PMID 24885608, 2014). "According to the National Comprehensive Cancer Network guidelines, ALK testing is not routinely performed in patients with squamous cell lung cancer." (PMID 24885608, 2014). "Patients with de novo MET amplifications showed the reduced response to the treatment with receptor tyrosine kinases TKI, while ALK negative squamous cell lung cancer patients with de novo MET amplifications showed major partial response to a dual MET/ALK inhibitor." (PMID 28806950, 2017). "However, there are single data reporting the incidence of ALK rearrangement in lung squamous cell carcinoma (1.3%) and not-otherwise specified NSCLC (4.5%)." (PMID 28534101, 2017).
Pleural effusion (46 papers, 2012 to 2025). The presence of an excessive amount of fluid in the pleural cavity. "The NGS of the paraffin-embedded section from pleural effusion revealed an ALK-positive mutation (EML4-ALK fusion)." (PMID 38978737, 2024). "After clinical model screening, we found that age, burr, pleural adhesion, maximum length, pleural effusion, calcification, ground glass opacity and tumor grade were associated with ALK mutation status by univariate logistic analysis in the training cohort." (PMID 33738250, 2021). "Regarding CT imaging, previous studies have demonstrated that a larger volume, solid mass, extensive lymph node metastasis, pleural invasion, pleural effusion and distant metastasis are associated with ALK positivity, suggesting a highly aggressive feature." (PMID 32690092, 2020). "In terms of conventional CT features, ALK mutated lesions were found to have larger size and hyper-attenuation, and tended to be solid, lobulated, with more prevalence of pleural effusion, pericardial effusion, and local lymphadenopathy (P < 0.01)." (PMID 32266148, 2020). "Recent studies have identified some CT imaging features that are associated with ALK gene rearrangements, including central tumor location, lobulated margin, solidity, pleural effusion, and distant metastasis." (PMID 32266148, 2020). "In contrast, ALK mutation was associated with pleural effusion." (PMID 35406429, 2022). "ALK rearrangement was linked to pleural effusion and lobulated margins." (PMID 35406429, 2022). "ALK rearrangement was linked to pleural effusion and lobulated margin." (PMID 35406429, 2022). "We further analyzed the 8 clinical features using multivariate logistic, and found 3 clinical variables with significant influence on the model (age, burr and pleural effusion), among which 2 clinical features (age and pleural effusion) were independent predictors of ALK mutation status." (PMID 33738250, 2021). "Moreover, three clinical features associated with ALK mutation (age, burr and pleural effusion) were also employed to construct a combined model of PET/CT and clinical model." (PMID 33738250, 2021). "After alectinib failure, the ALK fusion statuses of the primary tumor and pleural effusion were re-evaluated, but the genetic alteration remained detectable in both specimens." (PMID 38398169, 2024). "Presence of pleural effusion was found to be higher in patients with ALK gene rearrangement as seen in the previous studies; however, this was not statistically significant." (PMID 34514573, 2022). "In March 2017, lorlatinib was started, but the the third-generation ALK TKI was ineffective with a rapid clinical worsening with a massive pleural effusion." (PMID 35199053, 2022). "For the pleural effusion cfRNA detection, previous study showed that the pleural effusion cfRNA can successfully be extracted and achieving a 100% concordance rate of ALK fusion detection compared with cell blocks by PCR method." (PMID 33656807, 2021). "Clinical factors such as age, gender, histology, pleural effusion and gene mutations with epidermal growth factor receptor/anaplastic lymphoma kinase/ROS proto-oncogene 1 receptor tyrosine kinase (EGFR/ALK/ROS1) were analyzed." (PMID 30909993, 2019). "A few reports reported that compared with tumor tissue, pleural effusion cell block had 81.8% sensitivity and 80% specificity for detection of EGFR mutation and 62.5% to 100% sensitivity and 100% specificity for ALK detection." (PMID 27880851, 2016). "Both surgical resected samples and cell block from pleural effusion were tested positive for ALK rearrangement by both IHC and FISH." (PMID 27564104, 2016). "Our results were in accordance with previous report that 12.7% of ALK rearrangements were observed in malignant pleural effusion cell blocks from patients with advanced NSCLC." (PMID 26789109, 2016).
Pleural effusion (continued). "At the time of ALK rearrangements detection, 20 of the 24 patients were treatment naïve, while one patient was diagnosed as pleural effusion after adjuvant chemotherapy and another patient progressed from last line of chemotherapy." (PMID 27564104, 2016). "Cell block slides of pleural effusion fluid were successfully stained with IHC to detect the ALK protein." (PMID 25785456, 2015). "The most common extranodal sites in this patient population were skin (10%), lung (8%), and bone (6%) for ALK+ patients, and skin (16%), spleen (13%), liver (6%), and pleural effusion (6%) for ALK- patients." (PMID 22769020, 2012). "However, two months later, the patient developed bilateral pleural effusion, in which ALK-positive histiocytes were identified, indicating progressive disease." (PMID 36915094, 2023). "Moreover, the abnormal cells were positive for ALK on fluorescence in situ hybridization (15% in the pleural effusion sample and 2% in the bone marrow sample)." (PMID 33544280, 2021). "In our study, more false‐negative mutations were detected in the supernatant of pleural effusion in patients who had previously received targeted therapy and progressed, including one patient with false‐negative in detection of ALK fusion." (PMID 33656807, 2021). "Interestingly, our result also presented that ALK‐positive patients had significantly lower incidence of pleural effusion than both ALK‐ and EGFR‐negative patients." (PMID 28374971, 2017). "The most sensitive method for EGFR and ALK testing might be true only when the testing specimen is pleural effusion." (PMID 27352172, 2016). "The presence of ALK mutations is associated with a higher predilection for CNS metastasis, a higher risk of thromboembolic incidents, radiological presence of pleural effusion, central tumor location, absence of pleural tail and large pleural effusion." (PMID 39457620, 2024). "Since ALK expression is mostly silenced in the adult with the exception of neuronal tissue, the normal lung tissue, mesothelial lining, and inflammatory cells are devoid of ALK transcript, making ALK KD RT-PCR an ideal surrogate test for ALK fusion transcripts in lung or pleural effusion." (PMID 34559836, 2021). "An 11-year-old boy who complained of abdominal pain and cough was diagnosed with ALK-positive ALCL on the basis of systemic lymphadenopathy findings and immunohistochemistry results of pleural effusion." (PMID 33544280, 2021). "We established cell culture models from biopsies or pleural effusions of NSCLC patients whose disease progressed on treatment with a first- and/or second-generation EGFR or ALK TKI and responded to a second- or third-generation inhibitor." (PMID 29241554, 2017). "Pleural effusion was significantly less common among KRAS-positive patients, compared to EGFR-positive patients or ALK-positive patients (p = 0.046 and p = 0.026, respectively)." (PMID 27518729, 2016). "Pleural effusion was significantly less common among KRAS-positive patients, compared to EGFR-positive patients and ALK-positive patients (p = 0.046 and p = 0.026, respectively)." (PMID 27518729, 2016). "After 8 weeks of alectinib treatment, ALK-fusion-positive cells in the patient’s mediastinal lymph nodes decreased but ALK fusion-negative malignant cells increased in the pleural effusion." (PMID 38398169, 2024). "In this study, we performed a genome-wide knockout CRISPR/Cas9 library screening in an ALK-positive NSCLC line derived from pleural effusion without ALK-TKI therapy." (PMID 37917191, 2023). "The tumor cells in the pleural effusion were all negative for immunohistochemical markers (TTF-1 and Napsin A) and lung-specific oncogenic driver alterations (EGFR mutation and ALK translocation)." (PMID 30634950, 2019).
Pleural effusion (continued). "The pleural effusion of MGH021-2 and the core biopsies of MGH051-1 and MGH092-1 were cultured in TCM, -E, -I media on a layer of irradiated feeder fibroblasts, and their responses to ALK inhibitors were tested, similarly to the method described earlier." (PMID 29241554, 2017). "A computed tomography (CT) scan of the thorax revealed mediastinal lymphadenopathy and bilateral pleural effusions, suggestive of extranodal involvement of skeletal muscle in ALK-negative ALCL." (PMID 24393283, 2014). "Therefore, genome-wide CRISPR/Cas9 knockout screening was performed using an ALK+ NSCLC cell line established from pleural effusion without ALK-TKI treatment." (PMID 37917191, 2023). "In the univariate analysis, a PS of 2‐4, never smoking, driver mutations including those of EGFR and ALK, LDH ≥ 240 IU/L, CRP ≥ 1 mg/dL, NLR ≥ 4, liver metastasis, brain metastasis, pleural effusion, and steroid use at the commencement of nivolumab treatment were associated with a shorter PFS." (PMID 31880861, 2020). "Since there are few pre-clinical IBC models available to study the effects of the small molecule cMET/ALK inhibitor Crizotinib, we developed an ALK+ pre-clinical model of IBC using tumor cells freshly isolated from IBC patient with disease progression evidenced by pleural effusion." (PMID 24102046, 2013). "ALK‐positive NSCLC had more brain metastasis and less pleural effusion than double‐negative ones." (PMID 28374971, 2017). "Besides, ALK‐positive NSCLC had more brain metastasis and less pleural effusion than double‐negative ones." (PMID 28374971, 2017).